NRAS (NRAS proto-oncogene, GTPase)
Diseases named in the same sentence as NRAS in open-access papers (continued):
Sharing a sentence is not in itself a finding about the gene and the disease.
melanoma (continued). "Only KRAS/NRAS mutations in colorectal cancer do not result in discriminable protein profiles comparing wild-type and mutated cases, whereas an effect can be observed for thyroid cancer and melanoma." (PMID 30442178, 2018). "For example, our finding that the MEK inhibitor Cobi used as a single agent can inhibit the lytic capacity of T cells might be of importance in studies using MEKi without BRAFi in the setting of melanoma with non-mutated BRAF but mutated NRAS." (PMID 29346301, 2018). "Moreover, NRAS may serve as a biological marker to identify melanoma patients who can benefit from targeted therapies." (PMID 29682098, 2018). "The inactivation of p16CDKN2A is due to either genetic (mutations, deletions) or epigenetic (promoter methylation) mechanisms, whereas the amplification of CCND1 is particularly frequent in melanomas negative for BRAF/NRAS mutations, in chronically sun-exposed skin areas." (PMID 30218391, 2018). "Altogether our data demonstrate that co‐targeting BET and MEK elicits potent anti‐tumor effects in highly drug‐resistant NRAS‐mutant melanoma models and support the premise that BETi/MEKi combinations may be a valuable salvage strategy for MAPK and immune checkpoint inhibitor‐resistant tumors." (PMID 29650805, 2018). "In contrast to the inhibition of proliferation of NB xenografts observed in the present study, BRAF V600E-mutated melanoma cells showed increased proliferation upon dietary intervention with an LCT-based KD (75% fat), whereas NRAS Q61K-mutated and wild-type melanoma cells were not affected." (PMID 29029389, 2017). "Additionally, NRAS mutation status was reported as a predictor of poorer outcomes with lower median survival compared to non-NRAS mutated melanoma." (PMID 28668077, 2017). "The capacity of NF1 mutations to act both cooperatively and exclusively without BRAF and NRAS mutations in melanoma may be mediated through pathways other than the MAPK pathway." (PMID 28637487, 2017). "Mutations and overexpression of the neuroblastoma RAS viral (v‐ras) oncogene homolog (NRAS) are found across multiple tumor types and are common in highly metastatic cancers such as tumors of unknown primary, melanomas, and sarcomas that display a striking propensity for lung metastasis." (PMID 28341702, 2017). "Furthermore, we extended this observation to NRAS mutant melanoma." (PMID 28147313, 2017). "Consequently, the MBZ+trametinib combination may represent a potential therapy in NRAS mutant melanoma cells." (PMID 28157711, 2017). "To better understand the chromosome mechanisms leading to NRAS mutant allele increase in the proportion of NRAS mutated melanoma, we firstly performed FISH analyses with 2 BAC probes covering NRAS region and another region of chromosome 1, telomeric to this gene, in a large series of 104 melanomas." (PMID 28668077, 2017). "Thus, we provide evidence that Usp9x plays an important role in Ets-1 regulation and melanoma tumorigenicity, in part through NRAS transcription which may be of particular importance in tumours driven by NRAS mutation." (PMID 28198367, 2017). "For melanoma treated with BRAF inhibitors, resistance generally occurs within the first year and usually involves reactivation of the MAPK pathway by the acquisition of secondary NRAS or MEK mutations or alternative splicing or amplification of the BRAF gene itself." (PMID 28484715, 2017). "Therefore, the compensatory effects of RAF kinases is a conserved mechanism between human and murine NRAS-driven melanoma, since neither CRAF, nor BRAF loss alone is sufficient to block melanoma cell proliferation in both species." (PMID 28497782, 2017).
melanoma (continued). "These treatments may be effective for melanoma regardless of the mutation status of BRAF or NRAS and may help overcome melanoma's resistance to current treatments." (PMID 27086916, 2017). "Furthermore, the c-Met receptor to which HGF binds exclusively is expressed and activated in melanoma cells and tumours, especially in those that harbour the NRAS mutation and non-mutated BRAF." (PMID 28708099, 2017). "In addition, the melanoma short-term culture carrying an activating NRAS mutation (NRAS G13R) (Ma-Mel-93) was used (data not shown)." (PMID 27903987, 2017). "However, unlike in haematological malignancy, acquired copy-neutral LOH was not a predominant mechanism of mutant allele imbalance in NRAS Q61 mutated melanomas; indeed this aberration was detected in only 23% of our samples." (PMID 28668077, 2017). "Therefore, we conducted an unbiased assessment of Usp9x-regulated ubiquitination in NRAS mutant melanoma to define potential targets and pathways that could mediate NRAS regulation." (PMID 28198367, 2017). "Thus, CRAF is a bona fide alternative oncogene for BRAF/NRAS/GNAQ/GNA11 wild type melanomas." (PMID 27273450, 2016). "CPI-17 was consistently and highly overexpressed (4 of 4) in melanoma samples containing neither oncogenic BRAF V600E nor oncogenic NRas Q61K/R mutations; suggesting that Ras activity may primarily be driven via the CPI-17-ERM pathway in these cells." (PMID 27793041, 2016). "Interestingly, the EPHB6G404S mutation occurred significantly more frequently in melanomas without detectable BRAF or NRAS mutations." (PMID 27191502, 2016). "Previously, it was suggested that Ral activation may contribute to melanoma tumorigenesis and that Ral-A is frequently activated in human melanoma cell lines independent of NRAS mutations." (PMID 26993606, 2016). "Approximately 40%–50% of melanoma patients have activating mutations in BRAF at valine 600 (90% are BRAFV600E) and another 15%–25% have mutations in the neuroblastoma RAS viral oncogene homolog (NRAS), and either alteration results in constitutive activation of the MAPK pathway." (PMID 27598148, 2016). "Mutation status was also significantly associated with the site of the primary tumor (P= 0.004, Chi-square test); BRAF and NRAS mutations were relatively more common in melanomas from the trunk (23.6% and 21.0%) compared to tumors without mutations detected (Wild Type) (15.3%)." (PMID 27191502, 2016). "However, we also identified three interferon-stimulated genes (ISGs)—IFI6, IFI27, and MX1—that have not been previously implicated in oncogenic NRAS-induced transformation and melanoma tumor growth." (PMID 27608486, 2016). "Authors have demonstrated in melanomas wild type for NRAS and BRAF, that activating constitutively KIT mutations may be functionally equivalent to constitutive activation of the RAS-RAF-MEK-ERK pathway due to NRAS or BRAF." (PMID 26863566, 2016). "Thus, sensitivity or resistance to the combination did not associate with mutant BRAF or NRAS status in melanoma cell lines." (PMID 27447557, 2016). "One melanoma was wild-type for BRAF and NRAS (M214) with an unknown driver mutation." (PMID 27545456, 2016). "The results here suggest that the use of this combination is a promising treatment strategy for melanoma regardless of the mutation status of BRAF or NRAS, and it may overcome melanoma's resistance to current treatments." (PMID 27829238, 2016). "However, which specific mutation is a precursor of the disease is still controversial since a number of studies concluded that the mutation of BRAF or NRAS genes are not specific for the progression of nevus to melanoma." (PMID 27313934, 2016). "In addition, we find that the observed response is present for BRAF-mutated, but not NRAS-mutated melanoma cells, supporting these responses as on-target effects of the BRAF inhibitors." (PMID 27648299, 2016). "Therefore, targeting the cell cycle via CDK inhibitors in NRAS-mutant melanoma may be a promising strategy." (PMID 25537510, 2015).
melanoma (continued). "Our observations could lead to improvements in understanding the effects of NRASQ61 mutations in melanoma and drug development for NRAS-mutant or pan-negative melanomas." (PMID 25537510, 2015). "Thus, THRB-linked processes and the association between hypothyroidism and NRAS-mutant melanoma should be further experimentally validated, as thyroid hormone therapy might be a novel strategy for NRAS-mutant melanoma treatment." (PMID 25537510, 2015). "We found that NRAS mutation and the loss of PTEN may coexist in human melanoma." (PMID 26307673, 2015). "The two most common and studied events are activating mutations in the oncogene NRAS (15–20%), and loss of expression or function of the tumor suppressor PTEN (11–60%), but mutations of PI3K and AKT3, the predominant AKT isoform in melanoma, have also been described." (PMID 26356562, 2015). "Moreover, to improve the growth inhibitory effect of the PRi in NRAS mutant melanomas and to block the feedback mechanisms that may reactivate the MAPK pathway upon the treatment with a single drug, a MEKi can be used in combination." (PMID 25645078, 2015). "However, treatment options remain limited for the patients that lack mutations in the five most commonly mutated melanoma genes (BRAF, NRAS, KIT, GNAQ and GNA11) and the prognosis of such patients is particularly pool with a median overall survival of less than 1 year." (PMID 26424083, 2015). "In this study, we demonstrate high levels of cytoplasmic hnRNP K in tissue samples of malignant melanoma (MM) and MM metastases compared to benign nevi; moreover, we show for the first time that presence of hnRNP K is essential for DNA damage repair upon IR in NRAS-mutant MM cells." (PMID 26136337, 2015). "In the present study, we analyzed the impact of MEK inhibition on DNA damage response and cell survival upon ionizing radiation in NRAS-mutant malignant melanoma cells and show first evidence for the hypothesis that a functional cellular DDR in MM requires MAPK-mediated upregulation of hnRNP K." (PMID 26136337, 2015). "In this study we sought to investigate NRAS mutant lung cancer and neuroblastoma cell lines and showed that certain small molecule inhibitor combinations could also be used in NRAS mutant cancers other than melanoma." (PMID 25277205, 2014). "As all of the melanoma lines tested responded to treatment in a similar manner in the in vitro assays, we chose to perform the mouse xenograft experiments with the WM1366 cell line (CDK2 low/NRAS mutated) to assess if the compound would still be effective if CDK2 levels were low." (PMID 23527225, 2013). "As it has been previously shown that the BRAF V600E mutation conveys sensitivity of melanoma cells to BRAF and MEK inhibitors and the phenothiazine compounds, we next addressed whether the presence of a BRAF or NRAS mutation conferred sensitivity to dinaciclib." (PMID 23527225, 2013). "Furthermore, melanomas on skin that have not been chronically exposed to sun usually carry either a mutated NRAS or mutated BRAF (somatic mutations in such genes have been reported as mutually exclusive)." (PMID 23987572, 2013). "Melanomas present on mucosal membranes, acral skin (soles, palms, and nail bed), and on chronic sun-induced damage areas often do not have mutations within the genes of MAP kinase pathway such as BRAF and NRAS, which are commonly mutated in intermittent sun-exposed areas." (PMID 22333219, 2012). "Here, in melanocytes and in melanoma cell lines, we have studied the phosphorylation status of key PKB, mTOR and MAPK pathway components downstream of PTEN, PIK3CA, NRAS and BRAF mutations to determine whether the activity of the signalling pathways correlates with the upstream mutation." (PMID 22475322, 2012).
melanoma (continued). "Confirming previously reported data, BRAF and NRAS mutations were mutually exclusive in our patients' collection; overall, BRAF or NRAS mutations were detected in 23/34 (68%) primary tumours and 24/35 (69%) lymph node metastases from the same melanoma patients." (PMID 19799798, 2009). "In addition, loss of PTEN protein and oncogenic activation of NRAS seem to be mutually exclusive and both alterations may cooperate with the loss of CDKN2A expression in contributing to melanoma tumorigenesis." (PMID 19828018, 2009). "Here, we report that the mTOR inhibitor sapanisertib improves the efficacy of combined belvarafenib and cobimetinib therapy in NRAS, NF1, and KIT-mutant melanomas." (PMID 42091854, 2026). "Comparing transcptomics of MRGPRX4-driven tumors shows a broad overlap with BRAF/NRAS-driven tumors; however, the MRGPRX4 model also enriches an ECM-rich, invasive neural crest-like melanoma state." (PMID 42282710, 2026). "This study increases our understanding of biomarkers NRAS and KIT and provides a foundation for optimizing melanoma care, contributing to advancements in precision oncology." (PMID 41378737, 2026). "To extrapolate the implications of our findings and to further evaluate the potential clinical significance of NRAS ASO intervention, we conducted an in vivo study in mouse models carrying melanoma D04 cell line-derived xenografts." (PMID 40473796, 2025). "The efficacy of NRAS ASO-1 and NRAS ASO-2 was assessed in two NRAS-mutant melanoma cell lines at four time points, showing that the treatment can reduce NRAS-mRNA levels by up to 95%, with a peak depletion observed between 48 and 72 h." (PMID 40473796, 2025). "They act independently of subcellular target localization, reduce NRAS-mRNA levels, inhibit MAPK signaling, induce apoptosis, and suppress melanoma growth in vitro and in vivo." (PMID 40473796, 2025). "Inulin and mucin drive distinct changes in the microbiota, with inulin limiting tumor growth in colon cancer and NRAS mutant melanoma models and enhancing the efficacy of a MEK inhibitor against melanoma while delaying drug resistance." (PMID 40549339, 2025). "Actionable gene alterations in BRAF, NRAS, NF1, and KIT are common in Japanese patients with melanoma." (PMID 39823560, 2025). "Here, we explore the nanoscale clustering of NRas and PI3K in melanoma cells and investigate how these clusters contribute to signaling fidelity and cellular behavior." (PMID 41373795, 2025). "Here, we modulated mitochondrial dynamics of NRAS melanoma using mdivi-1, a DRP1 inhibitor, which sensitized NRAS mutant melanoma to vemurafenib." (PMID 40141318, 2025). "Notable findings include NRAS Q61L melanomas being enriched for modules involving C19orf10 and ARF4, while BRAF V600E melanomas were enriched for modules involving ALAS1 and MYO1B." (PMID 39796775, 2025). "In the TCGA cohort, the four distinct subtypes of melanoma (TCGA-SKCM), BRAF, NRAS, triple wild type, and NF1 put together, constitute only 25% of the samples, leaving ~75% with no clear mutation association." (PMID 41368197, 2025). "Using multi-color single molecule localization microscopy (PALM and dSTORM), we resolved the mutual nanoscale organization of NRas, PI3K, and BRAF at the plasma membrane of fixed and live melanoma cells." (PMID 41373795, 2025). "Further studies are required to assess these observations in other NRAS-mutant tumor cells in order to generalize the findings and also to explore these alterations in vemurafenib-resistant BRAF-mutant melanoma cells." (PMID 40141318, 2025). "According, DANCR is highly expressed across all four melanoma genomic subtypes (NRAS, NF1, BRAF, and triple negative) in The Cancer Genome Atlas (TCGA) genomic and transcriptomic data and in all melanoma cell subpopulations within a heterogeneous tumour model." (PMID 41336739, 2025).
melanoma (continued). "Given the therapeutic implications of NTRK fusions, molecular screening for these alterations is recommended in BRAF, NRAS, and KIT wild-type melanomas." (PMID 40508177, 2025). "Molecular parallels between COM and human melanoma, particularly MAPK pathway alterations and genes like BRAF, NRAS, MITF, and NF1, further support this study’s relevance." (PMID 40647405, 2025). "As expected, NRas and PI3K resided in mutual clusters at the plasma membrane of the 108T melanoma cells." (PMID 41373795, 2025). "To gain insights into the mechanisms underlying NK-mediated resistance to ICB, we analyzed the cellular composition of NRAS;Ink4a and YUMM5.2 melanomas across cohorts by scRNA-seq." (PMID 40530504, 2025). "In conclusion, our study revealed that actionable gene alterations in BRAF, NRAS, KIT, and NF1 are common in Japanese patients with melanomas." (PMID 39823560, 2025). "ROCK inhibitors also overcome targeted therapy resistance: Y-27632, GSK269962A, or fasudil restore BRAF inhibitor efficacy in melanoma, and ROCK1 silencing sensitizes BRAF/NRAS-mutant cells to MAPK inhibitors." (PMID 40368918, 2025). "The interplay between NRAS, KRAS and HRAS in the context of NRAS-mutant melanoma and other tumor types remains poorly understood." (PMID 40473796, 2025). "In this study, we applied two-color PALM and a combination with dSTORM (all in TIRF mode) to resolve the mutual nanoscale organization of NRas, PI3K and BRAF at the PM of 108T melanoma cells." (PMID 41373795, 2025). "VHL-Mb24 reduced ERK phosphorylation levels following EGF stimulation of NRAS expressing RASless HEK cells but did not affect ERK phosphorylation levels in NRASQ61L-mutant WM-1366 melanoma cells." (PMID 39379700, 2024). "CM has a high mutation load, and targeted therapy is an important therapeutic method for melanoma with driver gene alterations (i.e., BRAF, NRAS, and KIT)." (PMID 38229080, 2024). "STK19 kinase was a potential therapeutic target for NRAS-mutant melanomas; 5 and 20 μmol/L chelidonine inhibited STK19, and reduced the phosphorylation of NRAS S89, MEK, ERK1/2, and AKT in all four NRAS-mutant melanoma cell lines." (PMID 39598801, 2024). "We also report the different distributions of major oncogenic melanoma alterations (BRAF, NRAS, KIT) among different immune subtype groups." (PMID 38397409, 2024). "BRAF and NRAS mutant melanomas histopathologically correlate with low cumulative sun damage (low-CSD) melanomas, while NF1 mutant melanomas are classified as high-CSD." (PMID 38611025, 2024). "Although so far, only BRAF is targetable, the establishment of NRAS and NF1 status is important as it will allow further research on the influence of these genes on the clinical behavior of melanoma." (PMID 39340537, 2024). "Moreover, its previously established role in the negative control of ERK signaling in BRAFV600E as well as NRAS-mutant melanoma cells suggested that DUSP6 loss could drive the observed ERK hyperactivation." (PMID 39436655, 2024). "All the canine and equine melanoma cell lines retained their wild-type status of BRAF exon 15 and 11, NRAS exon 3, and KIT exon 11 according to WES." (PMID 38397192, 2024). "The clinically characterized tumor molecular subtypes included BRAF, NRAS, KRAS, KIT, and PIK3CA mutant melanomas, with BRAF mutant melanomas being more prevalent in AYA compared to adult patients (77% vs 41%; Fisher’s exact test, P = 0.0003)." (PMID 38589406, 2024).